PRELID1P6 (PRELID1 pseudogene 6)
Gene: Processed pseudogene on chromosome 2 (63,622,178 to 63,622,831, reverse strand). Ensembl gene ENSG00000228305.
Diseases named in the same sentence as PRELID1P6 in open-access papers:
PRELID1P6 is named in the same sentence as 1 disease in open-access papers, as found by Europe PMC text mining. Sharing a sentence is not in itself a finding about the gene and the disease. The quoted sentences say what the papers report.
glioma (3 papers, 2021 to 2024). A benign or malignant brain and spinal cord tumor that arises from glial cells (astrocytes, oligodendrocytes, ependymal cells). "We found that mRNA level of PRELID1P6 was highly upregulated in glioma and was associated with a shorter survival time." (PMID 34108621, 2021). "Mechanistically, PRELID1P6 inhibits the ubiquitin-mediated degradation of hnRNPH1, thus promoting glioma cell proliferation by the Akt/mTOR signaling pathway." (PMID 34108621, 2021). "Together, our data suggested that PRELID1P6 promotes cell proliferation and inhibits glioma cell apoptosis." (PMID 34108621, 2021). "Functional assays showed that PRELID1P6-promoted glioma cell proliferation and inhibited cell apoptosis, suggesting that PRELID1P6 promotes glioma progression." (PMID 34108621, 2021). "qRT-PCR confirmed that the expression of PRELID1P6 was significantly downregulated or upregulated in glioma cell lines." (PMID 34108621, 2021). "We explored the clinical significance of PRELID1P6 in glioma and found that high expression of PRELID1P6 was related to a poor prognosis." (PMID 34108621, 2021). "Collectively, we summarized that the knockdown of PRELID1P6 inhibited glioma progression via the hnHNPH1-Akt/mTOR pathway axis." (PMID 34108621, 2021). "This study aimed to show that pseudogene PRELI domain-containing 1 pseudogene 6 (PRELID1P6) promotes glioma progression." (PMID 34108621, 2021). "Collectively, our results showed that hnRNPH1 is important for PRELID1P6-promoted glioma proliferation." (PMID 34108621, 2021). "In the present study, we found that hnRNPH1-promoted glioma proliferation and interacted with PRELID1P6." (PMID 34108621, 2021). "Because we found that PRELID1P6 plays an oncogenic role in glioma and PRELID1P6 inhibited the ubiquitin-mediated degradation of hnRNPH1, we next investigated the impact of hnHNPH1 on glioma cell proliferation." (PMID 34108621, 2021). "Collectively, our results suggested that PRELID1P6 is highly expressed in glioma and high expression of PRELID1P6 predicts a shorter survival of glioma patients." (PMID 34108621, 2021). "Multivariate Cox regression analysis indicated that the downregulation of PRELID1P6 and IDH mutation were independent prognostic factors for glioma patients (P < 0.001 and P = 0.024, respectively)." (PMID 34108621, 2021). "Because hnRNPH1 is vital for PRELID1P6-promoted glioma proliferation, we also detected the phosphorylation levels of Akt/mTOR signaling pathway proteins after hnRNPH1 knockdown." (PMID 34108621, 2021). "PRELID1P6 mediates ubiquitin-mediated degradation of hnRNPH1 and promoting glioma proliferation." (PMID 36348434, 2022). "Knockdown of hnRNPH1-promoted glioma cell apoptosis, although PRELID1P6 was overexpressed." (PMID 34108621, 2021). "Taken together, our findings indicate the pro-proliferation roles of PRELID1P6 in glioma." (PMID 34108621, 2021). "PRELID1P6-promoted glioma proliferation in vitro and in vivo." (PMID 34108621, 2021). "Pseudogene PRELID1P6 activates Akt/mammalian (or mechanistic) target of rapamycin (mTOR) pathway by increasing HNRNPH1-mediated TRF2 splicing and promoting glioma development." (PMID 38405130, 2024).